CHD4 (chromodomain helicase DNA binding protein 4)
Description:
ATP-dependent chromatin-remodeling factor that binds and distorts nucleosomal DNA. Acts as a component of the histone deacetylase NuRD complex which participates in the remodeling of chromatin. Localizes to acetylated damaged chromatin in a ZMYND8-dependent manner, to promote transcriptional repression and double-strand break repair by homologous recombination. Involved in neurogenesis (By similarity).
Synonyms: CHD-4; Mi-2b; Mi2-BETA; SIHIWES
Tractability: Small molecule: a structure with a bound ligand is known. PROTAC: UniProt records ubiquitination sites on it; ubiquitination databases record sites on it; its protein half-life has been measured; a small molecule that binds it is known.
Target class: Enzyme; Hydrolase
Gene: Protein-coding gene on chromosome 12 (6,570,081 to 6,614,982, reverse strand). Ensembl gene ENSG00000111642.
Subcellular location: Nucleus; Cytoplasm, cytoskeleton, microtubule organizing center, centrosome
Subcellular location (Human Protein Atlas): Nucleoplasm; Cytosol; Mitotic spindle
Pathways (Reactome):
Gene expression (Transcription): ERCC6 (CSB) and EHMT2 (G9a) positively regulate rRNA expression; RNA Polymerase I Transcription Initiation; Regulation of endogenous retroelements by KRAB-ZFP proteins; Regulation of endogenous retroelements by Piwi-interacting RNAs (piRNAs)
Chromatin organization: ChAHP complex assembly; HDACs deacetylate histones; Interaction of NuRD complexes with transcription factors; NuRD complex assembly
Developmental Biology: Differentiation of naive CD4+ T cells to T helper 2 cells (Th2 cells); Transcriptional regulation of brown and beige adipocyte differentiation by EBF2
Signal Transduction: NGF-stimulated transcription; Regulation of PTEN gene transcription
Disease: Potential therapeutics for SARS
Gene Ontology:
Molecular function: ATP hydrolysis activity; ATP-dependent chromatin remodeler activity; histone deacetylase binding; nucleosomal DNA binding; protein binding; RNA polymerase II-specific DNA-binding transcription factor binding; transcription coregulator binding; transcription corepressor activity; chromatin binding; DNA binding; histone binding; zinc ion binding; ATP binding; DNA-binding transcription factor binding
Biological process: chromatin remodeling; double-strand break repair via homologous recombination; negative regulation of gene expression; negative regulation of DNA-templated transcription; positive regulation of DNA-templated transcription; regulation of cell fate specification; regulation of stem cell differentiation; negative regulation of transcription by RNA polymerase II; regulation of synapse assembly; terminal button organization
Cellular component: centrosome; chromatin; chromosome, telomeric region; cytoplasm; membrane; nucleoplasm; nucleus; NuRD complex; protein-containing complex; RNA polymerase II transcription regulator complex; site of DNA damage; cerebellar granule cell to Purkinje cell synapse; protein-DNA complex
Genetic constraint (gnomAD): Loss-of-function variants: 35 observed, 242.28 expected, observed/expected ratio (o/e) 0.14, 90% interval 0.11 to 0.19. The upper end of that interval is the gene's LOEUF score, 0.19, which puts it in group 1 of 6, group 1 being the genes least tolerant of losing a copy. Missense variants: 1,325 observed, 2,508.1 expected, observed/expected ratio (o/e) 0.53, 90% interval 0.5 to 0.55. Synonymous variants: 900 observed, 883.74 expected, observed/expected ratio (o/e) 1.02, 90% interval 0.96 to 1.08.
Gene-disease validity (ClinGen):
ClinGen rates the evidence that CHD4 causes each of these diseases.
syndromic intellectual disability (autosomal dominant): Definitive. A intellectual disability that is part of a larger syndrome.
Cancer hallmarks: genome instability and mutations (suppresses)
Homologues: Orthologues: chimpanzee CHD4 (99% identical), macaque CHD4 (99% identical), dog CHD4 (99% identical), pig CHD4 (99% identical), rabbit CHD4 (99% identical), mouse Chd4 (99% identical), rat Chd4 (98% identical), guinea pig CHD4 (98% identical), tropical clawed frog chd4 (85% identical), zebrafish chd4a (78% identical). Paralogues in human: CHD5 (71% identical), CHD3 (69% identical), CHD7 (24% identical), CHD9 (23% identical), CHD6 (22% identical), CHD8 (22% identical), CHD2 (21% identical), CHD1 (20% identical), SMARCA4 (17% identical), SMARCA2 (17% identical), EP400 (16% identical), SRCAP (16% identical), and 18 more.
Diseases named in the same sentence as CHD4 in open-access papers:
CHD4 is named in the same sentence as 135 diseases in open-access papers, as found by Europe PMC text mining. Sharing a sentence is not in itself a finding about the gene and the disease. The quoted sentences say what the papers report.
breast cancer (31 papers, 2016 to 2025). A primary or metastatic malignant neoplasm involving the breast. "Mutations in CHD4 have been identified in breast cancer patients, affecting its ATPase subunit (Mi-2β), the primary catalytic unit of NuRD, which also includes histone deacetylases HDAC1 and HDAC2." (PMID 40650308, 2025). "CHD4 is an epigenetic regulator linked to breast cancer and is being explored as a potential therapeutic target." (PMID 40650308, 2025). "In summary, we investigated the ERα-CHD4 interaction and its association with breast cancer progression." (PMID 38292202, 2024). "Particularly in breast cancer, chromosome amplification and mRNA up-regulation of CHD4 were observed, and higher expression of CHD4 is associated with poorer patient outcomes in triple negative (or basal) breast cancer cells." (PMID 38281186, 2024). "In conclusion, these findings provide novel insight into the molecular mechanism underlying ERα regulation and highlight a possible role for CHD4 as a biomarker that can benefit the development of hormone therapy for ERα-positive breast cancer." (PMID 38292202, 2024). "Access to HIF target genes within these regions is aided by proteins like Chromodomain-helicase-DNA-binding protein 4 (CHD4); a protein that is increasingly implicated in promoting stemness and chemoresistance in breast cancer." (PMID 39282472, 2024). "The present work examines mutations in CHD4 reported in patients with breast cancer and included in public databases and attempts to identify their roles in its development." (PMID 33981601, 2021). "We here review in vitro data arising from loss of function studies in different types of breast cancer cells using CHD4 knockdown models." (PMID 33981601, 2021). "Less attention has been paid to the role of CHD4 in breast cancer, and the known implications of CHD4 mutations in this pathological process are scarce." (PMID 33981601, 2021). "According to their location, it is clear that the majority of these putative CHD4 driver mutations in breast cancers negatively affect CHD4-ATPase and/or its remodeling activity." (PMID 33981601, 2021). "Remarkably, knockdown of Chd4 significantly reduced MMTV-NeuT cell growth (45%) and cell migration (46%) compared to the control, confirming that CHD4 is implicated in the development of HER2+ breast cancer, independently of the immunological context." (PMID 27779108, 2016). "To investigate CHD4-correlated mechanisms underlying the regulation of cell proliferation in breast cancer, we decided to examine the cell cycle progression of CHD4-silenced MCF10DCIS.com cells." (PMID 27779108, 2016). "Overall, CHD4 is associated with a complex signaling cascade and plays a vital role in the progression of breast cancer, and CHD4 might be associated with the worse prognosis of TNBC." (PMID 40004553, 2025). "CHD4 mRNA is up-regulated in all breast cancer subtypes, including ERα-positive breast cancer cells, suggesting that CHD4 expression may be a useful diagnostic tool for such patients." (PMID 38292202, 2024). "Clinically, the presence of CHD4 mutations in breast cancer cells creates different epigenetic settings that could impact the progression of breast cancer and modify the response to current therapies." (PMID 33981601, 2021). "More functional studies are needed to classify CHD4 mutations as driver or passenger mutations and to thus determine whether they contribute to breast cancer genesis." (PMID 33981601, 2021). "This heterogeneity of defects and consequences implies that the presence of CHD4 mutations in breast cancer cells may create different epigenetic frameworks that could affect the progression of breast cancer in interplay with mutations in other genes." (PMID 33981601, 2021). "According to data from in vitro and in vivo studies, some CHD4 mutations could play a role in breast cancer and confer sensitivity to current pharmacological BC treatments." (PMID 33981601, 2021).
breast cancer (continued). "Besides FP-RMS, CHD4 has been implicated in the viability of other tumors such as breast cancer, acute myeloid leukemia, lung cancer, and colorectal cancer." (PMID 32744500, 2020). "We previously reported that CHD3 and CHD4 are commonly mutated in a subset of breast cancers." (PMID 28649742, 2017). "The dramatic reduction of tumor growth induced by the loss of CHD4 is extremely relevant and suggests that the pharmacological inhibition of this gene could improve the treatment of the most aggressive breast cancer subtype." (PMID 27779108, 2016). "The eight CHD4 mutations identified here classified as putative drivers mutations could confer a growth advantage to cells carrying them and have been positively selected during the evolution of breast cancer." (PMID 33981601, 2021). "Furthermore, loss of CHD4 significantly reduced the S phase of breast cancer cells (16-19%)." (PMID 27779108, 2016). "Abolition of CHD4 impairs the recruitment of HDAC1 to the p21 promoter, resulting in the upregulation of anti-proliferative effector P21 (a cyclin-dependent kinase inhibitor protein), suggesting that CHD4 is a potential therapeutic target in breast cancer." (PMID 40004553, 2025). "The regulation of cell proliferation in HER2-positive breast cancer cell line with CHD4 depletion is explained by the observed increase in HER2 Tyr-1248 phosphorylation and subsequent inhibition of the downstream HER2/PI3K/AKT/ERK signaling cascade." (PMID 41278204, 2025). "CHD4 depletion causes accumulation of p62 and an increase in the LC3 II/I ratio, suggesting a block in late-stage autophagy in HER2-positive breast cancer cells, further contributing to growth arrest in cancer cells upon CHD4 loss." (PMID 41278204, 2025). "Breast cancer initiation and progression are connected by estrogen receptor α (ERα), positively coregulated with CHD4 expression." (PMID 40004553, 2025). "While CHD3 is considered as an oncogene and CHD4 a tumor suppressor, recent evidence demonstrates the role of CHD4 as an oncogene in breast cancers, as its amplifications are more common." (PMID 41278204, 2025). "Depletion of CHD4 in the BRCA1 mutant HCC1937 breast cancer cell line enhances the formation of g-H2AX foci, followed by a reduction in growth via cisplatin." (PMID 40004553, 2025). "CHD4 knockdown has been shown to inhibit MDA-MB-231 basal breast cancer cell growth in mouse xenograft model." (PMID 38281186, 2024). "Together, these data showed that CHD4 interacts with ERα in human breast cancer cells and were both located in the nucleus." (PMID 38292202, 2024). "Before assessing CHD4 and ERα interactions in breast cancer, we conducted Western blot analysis to determine CHD4 and ERα protein levels in various breast cancer cell lines and HEK293T cells." (PMID 38292202, 2024). "In the steady state, CHD4 depletion resulted in a primarily increased chromatin accessibility leading to abnormal gene expression unrelated to breast cancer cell identity." (PMID 38281186, 2024). "To further confirm the overlap between GATA3 and CHD4 in breast cancer cells, we performed CHD4 ChIP-seq in T47D cells, where both CHD4 and GATA3 are endogenously expressed." (PMID 38281186, 2024). "In this study, we investigated the roles of CHD4 in steady state basal breast cancer cells and during mesenchymal-to-epithelial transition (MET)." (PMID 38281186, 2024). "Here, we determine the roles of CHD4 in enhancer licensing and maintenance in breast cancer cells and during cellular reprogramming." (PMID 38281186, 2024). "Our study discovered that CHD4 promoted ERα-positive breast cancer cell proliferation and up-regulated ERα protein in the absence of E2." (PMID 38292202, 2024). "In this study, we demonstrated that both CHD4 and ERα contribute to breast cancer progression while providing evidence of the regulatory processes and functional interplay between these two proteins." (PMID 38292202, 2024).
breast cancer (continued). "In unchallenged basal breast cancer cells, CHD4 modulates chromatin accessibility at transcription factor binding sites; its depletion leads to altered motif scanning and redistribution of transcription factors to sites not previously occupied." (PMID 36993416, 2023). "Here we determine the roles of CHD4 to enhancer licensing and maintenance in breast cancer cells and during cellular reprogramming." (PMID 36993416, 2023). "CHD4 overexpression is associated with poor prognosis in CRC, papillary thyroid carcinoma (PTC) and breast cancer." (PMID 36681835, 2023). "The expression of miR-1299 is downregulated in doxorubicin-resistant breast cancer cell lines and tissues, while a sharp upregulation has been seen for circ_0006528 and CHD4 in contrast with sensitive cancer cells." (PMID 36132137, 2022). "These authors also examined the role of CHD4 in tumor growth in an orthotopic breast cancer xenograft mouse model." (PMID 33981601, 2021). "Drug resistance is promoted in cancers associated with breast cancer genes (BRCA), which are sensitive to DNA-damaging agents, once the CHD4 expression decreases." (PMID 34142021, 2021). "In hypoxic breast cancer cells, CHD4 physically interacts with hypoxia-inducible factors (HIFs), promoting the progression of BC." (PMID 33981601, 2021). "This knowledge will help us address how CHD4 mediates the chemotherapeutic response, and thus identify which patients with breast cancer are more likely to benefit from the different treatments." (PMID 33981601, 2021). "In summary, CHD4 enriched at the chromatin regions near hypoxia response elements (HREs) induces a subset of HIF target genes in breast cancer cells in a setting of hypoxia and xenograft tumor." (PMID 33981601, 2021). "Inhibition of CHD4 results in the restoration of p21 expression and recovery of breast cancer cell sensitivity to cisplatin and poly ADP ribose polymerase (PARP) inhibitors." (PMID 34142021, 2021). "Summary of studies describing the clinical relevance of CHD4 expression as a biomarker of prognosis in different breast cancer patients." (PMID 33981601, 2021). "Kaplan–Meier analysis of the TCGA dataset revealed positive correlation between high CHD4 mRNA levels and the poor overall survival of patients with breast cancer." (PMID 33981601, 2021). "The clinical relevance of CHD4 and its function in p21 regulation in breast cancer have been analyzed using patient tissues and a bioinformatics approach." (PMID 33981601, 2021). "The clinical relevance of the role of CHD4 in BC has been confirmed by the different authors using in vivo patient data from various breast cancer databases." (PMID 33981601, 2021). "In our previous study, we found that CHD4 regulated the loss of E-cadherin and affected epithelial-mesenchymal transition (EMT), which promotes metastatic ability in breast cancer cell lines." (PMID 31438571, 2019). "Depletion of CHD4 sensitizes the CAMA1 breast cancer cell line to Vorinostat or leukemia cells to genotoxic agents and reduces tumor formation." (PMID 28055972, 2017). "Noticeably, for the first time, we show that CHD4 is an essential gene in breast cancer progression." (PMID 27779108, 2016). "Concerning the oncogenic role of CHD4 in HER2+ breast cancer, it seems likely that targeting CHD4 in HER2+ patients can be a valuable strategy to overcome resistance to approved drugs." (PMID 27779108, 2016). "With this work, we shed light on the mechanisms through which CHD4 stimulates breast cancer cell proliferation." (PMID 27779108, 2016).